POSTN (periostin)
Diseases named in the same sentence as POSTN in open-access papers (continued):
Sharing a sentence is not in itself a finding about the gene and the disease.
pancreatic cancer (continued). "Previous reports indicated that EGFR phosphorylation is one of the most common events in pancreatic cancer progression, and we discovered that EGFR phosphorylation was downregulated in periostin-shRNA lentivirus-transfected SW1990 and BxPC-3 cells, whereas the total amount of EGFR was unchanged." (PMID 29163770, 2017). "POSTN can activate the PI3K/AKT signaling pathway through αvβ3 integrin to increase cellular survival in colon cancer and through α6β4 integrin complex to promote invasiveness and resistance of pancreatic cancer cells to hypoxia-induced cell death." (PMID 26716408, 2016). "Moreover, several immunohistochemical studies have found possible correlations between periostin expression and lymph node metastasis in cancer cases including HNSCC, gastric cancer cholangiocarcinoma, thyroid cancer, pancreatic cancer and melanoma." (PMID 22952986, 2012). "Earlier reports suggested that periostin expression level was correlated with tumor aggressiveness and/or poorer survival in NSCLC, SCLC, neuroblastoma, colon cancers, thyroid carcinomas, oral squamous cell carcinoma and pancreatic cancer." (PMID 18086302, 2007). "Moreover, POSTN and THBS1 are related to pancreatic cancer development and patient survival." (PMID 38029961, 2024). "Therefore, periostin expression is defined as a negative prognostic marker for the patients with various cancer types, including pancreatic cancer." (PMID 36830807, 2023). "Notably, induction of periostin expression in activated HSCs was found to be strictly regulated by MAM-derived granulin, and depletion of granulin in KPC mice significantly diminished metastatic growth of pancreatic cancer cells." (PMID 29903049, 2018). "This is because, consistent with previous studies, periostin expression was extremely low in pancreatic cancer cells and was not influenced by CTHRC1, and periostin was also shown not to influence the CTHRC1 levels of cancer cells." (PMID 37444482, 2023). "Using this approach and verifying the data using individual gene expression data, we found that AGR2, CEACAM6, GNMT, PDIA2, POSTN, RBPJL, and S100P are upregulated in pancreatic tumor tissue as compared to non-tumor tissue from Black and White patients." (PMID 36812168, 2023).
lung cancer (44 papers, 2006 to 2025). A malignant neoplasm involving the lung. "Single‐cell and spatial analyses have shown that POSTN+CAFs are enriched in advanced non‐small cell lung cancer (NSCLC) tumours, associated with ECM remodelling, tumour invasion, and immune suppression." (PMID 40038875, 2025). "POSTN is associated with immune cell infiltration and immune escape in the lung cancer microenvironment, especially LUSC." (PMID 35508298, 2022). "In summary, we systematically investigated the diagnostic and prognostic significance of POSTN in lung cancer." (PMID 35508298, 2022). "High expression of periostin, as well as the aberrant expression of alternatively spliced isoforms of this gene, are also associated with poor prognosis in primary lung cancer." (PMID 33014869, 2020). "Recent studies have also shown that periostin can be detected in the serum of NSCLC patients, indicating the possible utility of periostin as a cancer-associated glycoprotein in lung cancer." (PMID 32719746, 2020). "In lung carcinoma, the expression of periostin has been linked to tumor invasiveness and metastasis." (PMID 32719746, 2020). "To investigate associations between periostin expression and clinical outcomes, we examined specimens from 189 cases of lung cancer by immunohistochemistry (IHC) using anti-periostin staining." (PMID 30131847, 2018). "Combining multi-database predictions with experimental validation (such as ChIP-qPCR) to identify POSTN-specific upstream regulators may further discover emerging regulatory networks for recurrence risk in lung cancer patients." (PMID 40991535, 2025). "Indeed, we found that high POSTN expression was associated with poor prognosis in kidney papillary cell carcinoma, liver cancer, and lung cancer." (PMID 36172351, 2022). "In lung cancer, the expression of periostin has been linked to tumor invasive and metastasis." (PMID 32719746, 2020). "The analysis revealed a significant upregulation of POSTN in SCLC as well as other lung cancer types when compared to normal tissues." (PMID 39762921, 2025). "Serum POSTN level is also aberrantly upregulated in lung cancer, and high POSTN level contributes to increasing T-stage and N-stage of patients with SCLC." (PMID 39762921, 2025). "The elevated periostin levels in the serum of transverse aortic constriction (TAC)-operated was causatively associated with larger orthotopic breast and lung cancer tumors and a higher rate of metastatic spread." (PMID 40915108, 2025). "An in vitro study showed that incubation with periostin enhanced the proliferation of breast and lung cancer cells." (PMID 38279150, 2024). "For example, CAFs have been proven to secrete many cytokines or growth factors, such as IL‐6, periostin, hepatocyte growth factors, and insulin‐like growth factors, mediating an osimertinib‐resistant phenotype in lung cancer cells." (PMID 39036343, 2024). "TAC-operated mice with orthotopic breast and lung cancer had shown enhanced tumor growth and it was found that cardiac expression and plasma levels of periostin and connective tissue growth factor (CTGF) were increased." (PMID 38279150, 2024). "Our results demonstrated that metformin drug resistance increases the expression of proinflammatory and invasive genes, including BMP5, CXCL3, VCAM1, and POSTN, in A549 lung cancer cells." (PMID 37239373, 2023). "Periostin is overexpressed in many cancer types, including BC, lung cancer, colorectal cancer, and liver cancer." (PMID 37922300, 2023). "The results are consistent with those reports that POSTN was up in several tumour tissues, including lung cancer tissues." (PMID 35508298, 2022). "Our results showed that the overexpression of POSTN was associated with poor OS and PFS in lung cancer." (PMID 35508298, 2022). "We found that upregulated POSTN can be a promising biomarker to predict the prognosis of patients with lung cancer." (PMID 35508298, 2022).
lung cancer (continued). "In this study, the pan-cancer analysis revealed that POSTN was upregulated in lung cancer patients with poor prognoses." (PMID 35508298, 2022). "The expression of POSTN was significantly correlated with most markers of multiple immune cell subtypes in lung cancer." (PMID 35508298, 2022). "To identify the biological implications of POSTN in lung cancer, we examined the genes that were correlated with POSTN in LUAD and LUSC using the LinkedOmics database." (PMID 35508298, 2022). "Consistent with studies related to other cancers, our results indicated that POSTN was involved in the motility and in vitro invasive potential of lung cancer cells." (PMID 35163164, 2022). "It was found that recombinant POSTN enhanced MMP-2 expression in a concentration-dependant manner, which confirms the results obtained earlier on A549 lung cancer cells transfected with POSTN-specific short hairpin (A549.shRNA)." (PMID 35163164, 2022). "The progression of lung cancer is also strongly related to the infiltration of immune cells, and our study now shows that Periostin is critical in this process, especially in neutrophil-dominant and macrophage-dominant inflammation." (PMID 35508298, 2022). "In lung cancer, the upregulation of POSTN correlates with the high proliferation and migration of human lung adenocarcinoma cell line (A549)." (PMID 35508298, 2022). "It was found that lung cancer cells with the silenced expression of POSTN (A549.shRNA) were characterized by decreased migratory capacity and invasiveness in vitro compared to control cells." (PMID 35163164, 2022). "POSTN mRNA expression in the dissected lung cancer cells was confirmed by laser capture microdissection and real-time PCR." (PMID 35163164, 2022). "We discovered that EV uptake increase the expression of SPP1, CD44, and POSTN genes in lung cancer cells." (PMID 36424413, 2022). "Based on transcript level expression study using quantitative real-time PCR showed five significantly differentially expressed genes SPP1, VEGFA, CD44, FOXO1 and POSTN in EVs cargo derived from lung cancer patients with bone metastasis." (PMID 36424413, 2022). "To clarify the role of POSTN in lung cancer progression, we analyzed the effect of POSTN silencing on the migration and invasiveness of lung cancer A549 cells." (PMID 35163164, 2022). "High levels of POSTN correlated with immune cell infiltration in lung cancer, especially lung squamous cell carcinoma (LUSC), which was further confirmed based on the results from the TISIDB database." (PMID 35508298, 2022). "In the current study, we analysed the expression of POSTN in various lung cancers using the Oncomine database and Timer database." (PMID 35508298, 2022). "Taken together, our finding emphasises that POSTN is related to poor prognosis and tumour immune infiltration in lung cancer patients." (PMID 35508298, 2022). "The overexpression of POSTN was strongly correlated with the immune cell infiltration in lung cancer patients with poor prognoses." (PMID 35508298, 2022). "Here, we confirmed that the overexpression of POSTN was correlated with several immune cell infiltration in lung cancer tissues, including B cells, CD8+ T cells, CD4+T cells, macrophages, neutrophils, and dendritic cells." (PMID 35508298, 2022). "POSTN was significantly upregulated in lung cancer patients who smoked compared to healthy controls, with no sex differences." (PMID 35508298, 2022). "The findings indicated that the overexpression of POSTN has a vital role in the progress of lung cancer and metastasis." (PMID 35508298, 2022). "All the genes except POSTN showed higher expression in lung cancer cells (A549, SK-Lu-1, and Calu3)." (PMID 35406434, 2022). "Several studies have confirmed that POSTN, MMP9, and VCAM1 are implicated in regulating the incidence and development of solid tumors such as lung cancer, gastric cancer, and rectal cancer." (PMID 35965624, 2022).
lung cancer (continued). "Our results indicated that POSTN silencing using shRNA (short-hairpin RNA) significantly inhibited the migratory and invasive capabilities of lung cancer cells (A549.shRNA) compared to control A549.CTRL cells." (PMID 35163164, 2022). "In lung cancer, POSTN mRNA expression has been detected mainly in the stromal cells surrounding the cancer cells, whereas very little expression was found in the cancer cells themselves." (PMID 33905434, 2021). "For example, as a tumor promoter, POSTN was only overexpressed in the stroma of prostate cancer, lung cancer, bladder cancer, and colorectal cancer." (PMID 33083453, 2020). "POSTN overexpression promotes proliferation and migration in A549 lung cancer cells and enhances proliferation in gastric cancer cell lines, and recombinant POSTN and POSTN derived from normal human dermis stimulate melanoma cell proliferation." (PMID 33488671, 2020). "In this study, we first analyzed N-glycoproteins including periostin expressions in lung cancer BALs by using MS-based analysis, and then, further validated our findings by ELISA assay." (PMID 32719746, 2020). "In the MS-based analysis, we found that the periostin was differentially expressed among all lung cancer types, with a relatively higher level in SQCC using the N-glycoprotein capture technique." (PMID 32719746, 2020). "Although we found a similar result in the subsequent ELISA assay among lung cancer types, the expression of periostin revealed a relatively higher level in ADC." (PMID 32719746, 2020). "LCM confirmed significantly higher POSTN mRNA expression in the stromal cells (CAFs) compared to the lung cancer cells." (PMID 32987711, 2020). "Recent studies have also shown that periostin can be detected in the serum of NSCLC patients, indicating the potential utility of periostin as a therapeutic target in lung cancer." (PMID 32719746, 2020). "Our finding is also in accordance with the observation of elevated serum levels of periostin in lung cancer." (PMID 32719746, 2020). "In this study, we investigated the profile of N-glycoproteins in BAL specimens and identified periostin to be significantly overexpressed in different subtypes of lung cancers." (PMID 32719746, 2020). "Based upon the fact that the majority of secreted proteins are glycoproteins, we have profiled N-glycoproteins in BAL collected from lung cancers, and investigated the expression of glycoproteins such as the matrix N-glycoprotein, periostin, in lung cancers." (PMID 32719746, 2020). "Among these differentially expressed glycoproteins in lung cancer, periostin was a particularly interesting one." (PMID 32719746, 2020). "Significantly higher mRNA expression of POSTN was observed in the microdissected stromal cells (CAFs) compared to lung cancer cells (**** p < 0.0001, Mann–Whitney U test)." (PMID 32987711, 2020). "We further investigated the expression of periostin in BAL using an independently collected cohort of lung cancer patients by an ELISA assay." (PMID 32719746, 2020). "In lung cancer, periostin promotes Twist and Snail expression by inhibiting miR-381 via the ERK and p38 signaling pathways." (PMID 31795469, 2019). "High serum periostin has been identified as a factor for poor prognosis in lung cancer, and periostin overexpression in NSCLC tissue, identified by IHC, is also correlated with a poor prognosis." (PMID 30131847, 2018). "Although periostin is known to support tumor development in human malignancies, little is known about its effect on lung-cancer progression." (PMID 30131847, 2018). "For example, overexpression of POSTN in the A549 lung cancer cell line promoted cell proliferation and migration by inducing vimentin and N-cadherin expression and downregulating E-cadherin expression." (PMID 29946533, 2018). "In a syngenic implantation model, murine Ex3LL lung-cancer cells formed smaller tumor nodules in periostin−/− mice than in periostin+/+ mice, both at the primary site and at metastatic lung sites." (PMID 30131847, 2018).
lung cancer (continued). "Online TCGA datasets demonstrate the prognostic relevance of periostin in lung cancer; a higher periostin level correlates with poor overall survival." (PMID 28977942, 2017). "The results indicated that periostin expression is positively correlated with Twist and Snail expression in lung cancer specimens." (PMID 28977942, 2017). "To confirm EMT phenotypes after periostin treatment, we assessed the mobility of lung cancer cells after periostin treatment in different assays (wound-healing, migration and invasion assays)." (PMID 28977942, 2017). "Here, we discuss the molecular mechanisms involved in periostin-induced promotion of EMT in lung cancer cells." (PMID 28977942, 2017). "To confirm the role of periostin in lung cancer metastasis, we examined A549 cells, which stably express periostin shRNA." (PMID 28977942, 2017). "To investigate the role of periostin in the process of EMT in lung cancer, we treated A549 and CL1-0 lung cancer cells with different doses of recombinant periostin." (PMID 28977942, 2017). "Our results indicate that treatment of lung cancer cells with periostin (100 ng/ml) increases the phosphorylation of ERK and p38 signaling proteins but not that of JNK." (PMID 28977942, 2017). "We have demonstrated that recombinant periostin promoted the EMT process in lung cancer cells in a dose-dependent manner (10-100 ng/ml)." (PMID 28977942, 2017). "Here, we report for the first time the mechanisms by which periostin promotes EMT in lung cancer cells via the ERK/p38 pathway." (PMID 28977942, 2017). "To investigate the role of periostin in lung cancer, we retrieved four datasets from the Oncomine database, which revealed that periostin expression levels were higher in tumor specimens than in normal tissues." (PMID 28977942, 2017). "Taken together, our study suggests that ceruloplasmin, lipocalin 2 and periostin are potential candidate biomarkers at early stages for lung cancer." (PMID 28088789, 2017). "In the present study, we show that periostin promotes EMT in lung cancer and also Twist and Snail expression by inhibiting miR-381 via the ERK and p38 signaling pathways." (PMID 28977942, 2017). "Our study provides a novel insight into the means by which periostin regulates the EMT process in lung cancer." (PMID 28977942, 2017). "Our IHC data indicate that periostin expression is positively correlated with Twist, Snail and tumor stage in lung cancer." (PMID 28977942, 2017). "We found that recombinant periostin induces the EMT phenotype in lung cancer cells through the p38/ERK pathway, while pretreatment with chemical inhibitors prevented periostin-induced EMT induction." (PMID 28977942, 2017). "Periostin is overexpressed in the tumor tissue of a number of human tumors, and a similar result is shown in the serum of lung cancer and thymoma patients." (PMID 24273600, 2013). "POSTN was found to be overexpressed in several human cancers including ovarian, colon, pancreatic, breast, lung cancer, and melanoma, with contradictory data concerning the identity of periostin-expressing cells (i.e. stroma, tumor cells or both)." (PMID 21611158, 2011). "The presence of the periostin protein was also shown in the stroma of ovarian, colon and lung carcinoma." (PMID 21611158, 2011). "Recently, our group has demonstrated that periostin as a marker for the epithelial-mesenchymal-transition (EMT) programme in lung cancer is prognostically relevant." (PMID 20534149, 2010). "For lung cancer, we measured a significant 5-fold increase of POSTN expression in NSCLC tumors (272 ± 177 vs 55 ± 49 for normal lung, P = 0.002)." (PMID 18086302, 2007). "Tumoural POSTN may also contribute to tumour growth and knockdown of POSTN in lung cancer cells repressed tumour growth in vivo." (PMID 39780187, 2025).